IFT140 (intraflagellar transport 140)
Description:
Component of the IFT complex A (IFT-A), a complex required for retrograde ciliary transport and entry into cilia of G protein-coupled receptors (GPCRs). Plays a pivotal role in proper development and function of ciliated cells through its role in ciliogenesis and/or cilium maintenance. Required for the development and maintenance of the outer segments of rod and cone photoreceptor cells. Plays a role in maintenance and the delivery of opsin to the outer segment of photoreceptor cells (By similarity).
Synonyms: KIAA0590; WDTC2; gs114; CED5; MZSDS; PKD9; RP80; SRTD9; c305C8.4; c380F5.1
Tractability: PROTAC: ubiquitination databases record sites on it; its protein half-life has been measured.
Gene: Protein-coding gene on chromosome 16 (1,510,427 to 1,612,075, reverse strand). Ensembl gene ENSG00000187535.
Subcellular location: Cytoplasm, cytoskeleton, cilium basal body; Cytoplasm, cytoskeleton, microtubule organizing center, centrosome; Cell projection, cilium
Subcellular location (Human Protein Atlas): Basal body; Mitochondria; Nucleoplasm
Pathways (Reactome):
Organelle biogenesis and maintenance: Intraflagellar transport
Signal Transduction: Hedgehog 'off' state
Gene Ontology:
Molecular function: protein binding; protein carrier chaperone
Biological process: cilium assembly; intraciliary anterograde transport; intraciliary retrograde transport; protein localization to cilium; protein localization to non-motile cilium; regulation of cilium assembly
Cellular component: centrosome; ciliary basal body; cilium; intraciliary transport particle A; axoneme; ciliary tip; centriole; non-motile cilium; photoreceptor connecting cilium; photoreceptor outer segment
Genetic constraint (gnomAD): Loss-of-function variants: 123 observed, 146.96 expected, observed/expected ratio (o/e) 0.84, 90% interval 0.72 to 0.97. The upper end of that interval is the gene's LOEUF score, 0.97, which puts it in group 4 of 6, group 1 being the genes least tolerant of losing a copy. Missense variants: 1,964 observed, 1,918.7 expected, observed/expected ratio (o/e) 1.02, 90% interval 0.99 to 1.06. Synonymous variants: 834 observed, 799.83 expected, observed/expected ratio (o/e) 1.04, 90% interval 0.98 to 1.1.
Gene-disease validity (ClinGen):
ClinGen rates the evidence that IFT140 causes each of these diseases.
autosomal dominant polycystic kidney disease (autosomal dominant): Definitive. Autosomal dominant form of polycystic kidney disease.
IFT140-related recessive ciliopathy (autosomal recessive): Definitive. Any ciliopathy in which the cause of the disease is biallelic variants in the IFT140 gene.
Homologues: Orthologues: chimpanzee IFT140 (99% identical), macaque IFT140 (96% identical), mouse Ift140 (82% identical), rat Ift140 (82% identical), dog IFT140 (81% identical), guinea pig IFT140 (81% identical), rabbit IFT140 (80% identical), pig IFT140 (75% identical), tropical clawed frog ift140 (64% identical), zebrafish ift140 (58% identical), Drosophila melanogaster rempA (34% identical), Caenorhabditis elegans che-11 (31% identical). Paralogues in human: IFT172 (19% identical).
Diseases named in the same sentence as IFT140 in open-access papers:
IFT140 is named in the same sentence as 78 diseases in open-access papers, as found by Europe PMC text mining. Sharing a sentence is not in itself a finding about the gene and the disease. The quoted sentences say what the papers report.
ciliopathy (22 papers, 2013 to 2025). A genetic disorder of the cellular cilia or the cilia anchoring structures, the basal bodies, or of ciliary function. "Because the Ift140 cKO mice exhibited growth retardation and premature death, it will be difficult to determine if causes of death are similar to that in complex human ciliopathies." (PMID 40348912, 2025). "Kidney organoids generated from patient-derived iPS cells with a compound heterozygous mutation in IFT140 recapitulate the phenotype of NPHP-associated ciliopathy, including shortened club-shaped primary cilia." (PMID 37209321, 2023). "We believe that it would be more appropriate to use the terms IFT140-associated ciliopathy or IFT140-associated dysplasia." (PMID 37628605, 2023). "The rarest phenotype of IFT140-associated ciliopathy is cranioectodermal dysplasia, which is frequently referred to as Sensenbrenner syndrome." (PMID 37628605, 2023). "Among the mutant lines in this study we found five genes which have been previously linked to human ciliopathies: B9d2, Cc2d2a, Rpgrip1l, Ift140 and Nek930." (PMID 31243271, 2019). "In this study, we used diagnostic WES to detect variants in IFT140 as a likely cause of a clinical ciliopathy phenotype of the patient and performed cellular ciliary phenotyping to investigate the pathogenicity of these variants." (PMID 30479745, 2018). "Hearing impairment has been described only once before to be part of the IFT140-related ciliopathy spectrum, when a patient with otherwise non-syndromic retinal dystrophy, carrying variants in IFT140, was described with progressive hearing loss." (PMID 30479745, 2018). "Segregation analysis in the parents showed bi-allelic inheritance that is in line with the expected recessive inheritance pattern of IFT140-associated ciliopathies." (PMID 30479745, 2018). "MZSDS was first classified as a ciliopathy when recessive mutations in IFT140 were reported to be causative, and it is now known also to be caused by dysfunction of IFT172." (PMID 28724397, 2017). "We propose a key role of Ift140 for motile cilia assembly in certain tissues and suggest that genetic alterations of IFT140 could be associated with motile ciliopathies." (PMID 40348912, 2025). "In comparison, SKAT-O identified only PKD1 and PKD2 after p-value adjustment, whereas PERADIGM identified an additional candidate gene, IFT140 is a well-established gene in ciliopathies that has recently been implicated as a monogenic cause of renal cyst formation." (PMID 41411243, 2025). "Mutations in IFT140 have been implicated in human nephronophthisis (NPHP)-associated ciliopathies." (PMID 37209321, 2023). "Pathogenic variants in IFT140 are associated with various phenotypes of ciliopathies." (PMID 37628605, 2023). "One cysts contained a pathogenic somatic mutation in IFT140, a ciliopathy gene that causes a cystic kidney phenotype, suggesting that this second hit could have had played a role in cyst initiation." (PMID 32163234, 2020). "Consistent with this, IFT140 ciliopathy patients often are compound heterozygous, with 1 allele being null and a second allele with a missense mutation." (PMID 38079449, 2023). "Many ciliopathy genes, such as CEP290, IFT140, and IQCB1 initially reported to cause syndromic retinal degeneration, but were later identified as having vital roles in LCA pathogenesis as well." (PMID 33957996, 2021). "With kidney organoids, the intraflagellar transport 140 (IFT140) gene was rescued in cells derived from a patient who had nephronophthisis (NPHP)-related ciliopathy (NPHP-RC)." (PMID 32671050, 2020). "The Ift140 gene was prioritised as a strong putative candidate due to the similarity of the cauli phenotype with other ciliopathy mouse models." (PMID 24009529, 2013). "IFT140, intraflagellar transport protein 140, a subunit of the IFT complex, is essential for retrograde transportation in cilia and mutations as well as dysregulation are linked to syndromic ciliopathies and male fertility." (PMID 37885041, 2023).
ciliopathy (continued). "Moreover, we suggest to describe the presented phenotypes as “IFT140-related ciliopathies with MZSDS- or CED-like features” to better represent a variable disease cohort." (PMID 35873489, 2022). "Instead “IFT140-related ciliopathy with MZSDS- and/or CED-like features” could be considered to better represent the phenotype of the patient." (PMID 35873489, 2022). "Moreover, we suggest an alternative description of MZSDS to better resemble the variability seen between patients within this cohort, i.e. “IFT140-related ciliopathy with MZSDS- or CED-like features”." (PMID 35873489, 2022). "Variants in IFT140 are implicated in the pathogenesis of CED and MZSDS, but also in JATD, Bardet-Biedl syndrome (BBS), Optiz trigonocephaly C syndrome (OTCS), and isolated retinitis pigmentosa (RP) displaying the complexity of ciliopathies." (PMID 35873489, 2022). "Crucially, mutations in IFT140 cause a spectrum of ciliopathies, including MZSDS, JATD, syndromic and non-syndromic retinal dystrophy, Opitz trigonocephaly C syndrome, and Sensenbrenner syndrome." (PMID 28724397, 2017). "For example, Sensenbrenner syndrome (also known as cranioectodermal dysplasia), a ciliopathy characterized by sagittal craniosynostosis with accompanying facial, skeletal, and ectodermal anomalies, is caused by mutations in the IFT-A genes IFT43, WDR35, IFT122, WDR19, and IFT140." (PMID 28724397, 2017). "It is possible that short cilia with diminished cilia beat frequency are a feature of acquired ciliopathies, particularly attributed to cigarette smoke exposure, perhaps due to interruption of IFT proteins including IFT140." (PMID 40348912, 2025). "Patient 1 was diagnosed with “IFT140-related ciliopathy with MZSDS-like features” and patient 2 with “IFT140-related ciliopathy with CED-like features”." (PMID 35873489, 2022). "In our literature review of a total of 161 articles, only a single ciliopathy case was reported in the IFT140 gene, and none in any BBS genes or the ALMS1 gene." (PMID 40225151, 2023). "Taken together, by combining genetic data, functional test results, and clinical findings we were able to accurately diagnose patient 1 with “IFT140-related ciliopathy with MZSDS-like features” and patient 2 with “IFT140-related ciliopathy with CED-like features”." (PMID 35873489, 2022).
Mainzer-Saldino syndrome (11 papers, 2013 to 2025). "Specifically, we systematically analyzed the ΔΔG of MVs in IFT140 to identify those potentially pathogenic and associated with Mainzer-Saldino syndrome (MSS)." (PMID 40337643, 2025). "Most frequently, pathogenic variants in IFT140 correspond to the phenotype of Mainzer–Saldino syndrome." (PMID 37628605, 2023). "In fact, pathogenic variation in IFT140 has also been reported in patients with Mainzer-Saldino Syndrome (MSS), Jeune Syndrome (JATD), Opitz trigonocephaly C syndrome (OTCS), and isolated retinal dystrophy." (PMID 32007091, 2020). "Mutations in IFT140 have recently been identified in Mainzer-Saldino syndrome (OMIM 266920) further expanding the rapidly growing collection of human disorders caused by defects in primary cilia function." (PMID 23469164, 2013). "Individual XV.30 carried a homozygous duplication of exons 27 to 30 (c.3454-488_4182+2588dup, p.Tyr1152_Thr1394dup) in the IFT140 gene, resulting in a Saldino-Mainzer syndrome." (PMID 40225151, 2023). "The p.(Gly522Glu) change has been previously reported in a patient with Mainzer-Saldino syndrome and is predicted to have a deleterious effect on the IFT140 protein." (PMID 32007091, 2020). "A further five individuals from four families returned a molecular diagnosis consistent with syndromic conditions (CLN3; Batten disease/AHI1; Joubert syndrome / IFT140; Mainzer‐Saldino syndrome) and were referred for clinical re‐evaluation." (PMID 29178642, 2017). "Bi-allelic pathogenic variants in IFT140 have been associated with the syndromic ciliopathy Short-Rib Thoracic Dysplasia 9 with or without Polydactyly (SRTD9 (MIM: 266920)), also known as Mainzer–Saldino Syndrome." (PMID 40428294, 2025). "Missense variants in IFT140 have been reported to lead to “short-rib thoracic dysplasia 9 with or without polydactyly” (SRTD9, MIM #266920), also known as Mainzer-Saldino syndrome or retinitis pigmentosa 80 (RP80, MIM #617781)." (PMID 38152138, 2023).
cystic kidney disease (9 papers, 2023 to 2026). A congenital or acquired kidney disorder characterized by the presence of renal cysts. "While SEC63 mutations rarely involve the kidneys, the co-existence of an IFT140 variant likely contributed to the development of bilateral renal cysts." (PMID 41994676, 2026). "A 9-gene cystic kidney disease panel revealed a pathogenic, heterozygous, frameshift variant c.1867_1870del p.Glu623Argfs*20 in IFT140 (GenBank ID: NM_014714.3), confirming a diagnosis of cystic kidney disease." (PMID 40282368, 2025). "A 9-gene cystic kidney disease panel revealed a pathogenic heterozygous splice site variant c.1359_1359+3delinsAC in IFT140 (GenBank ID: NM_014714.3), again confirming a diagnosis of cystic kidney disease." (PMID 40282368, 2025). "This study confirms that IFT140 LoF variants represent a strong contributor to renal cyst development." (PMID 40428294, 2025). "In this study, we sequenced up to 92 genes associated with inherited cystic kidney disease, including IFT140, in 157 adult patients with polycystic kidneys whose parents did not have evident polycystic kidneys." (PMID 39291187, 2024). "In this study, we sequenced up to 92 genes associated with inherited cystic kidney disease, including IFT140 in adult patients with polycystic kidneys whose parents do not have evident polycystic kidneys." (PMID 39291187, 2024). "We previously generated a floxed allele of Ift140 and showed mice exhibited severe postnatal cystic kidney disease with Ift140 deletion targeting the kidney collecting ducts and also retinal degeneration with deletion in photoreceptor cells." (PMID 38079449, 2023). "We sequenced up to 92 genes associated with inherited cystic kidney disease, including IFT140." (PMID 39291187, 2024). "Moreover, hypomorphic or missense mutations in IFT140 may cause milder, tissue-specific conditions, such as retinitis pigmentosa or isolated renal cysts." (PMID 40615527, 2025). "We highlight two cases initially suspected as PKD, later confirmed by genetic testing as IFT140-related cystic kidney disease." (PMID 40282368, 2025). "About 30% of cystic kidney disease variants were found in patients aged > 75 years, including variants in 4 genes causing ADPKD-like disease spectrum (ALG5, ALG9, DNAJB11, and monoallelic IFT140)." (PMID 40677324, 2025). "The patient's cystic kidney disease presentation was attributed to the truncating IFT140 variant rather than PKD1 VUS." (PMID 37962562, 2024).
Retinal dystrophy (8 papers, 2017 to 2024). Retinal dystrophy is an abnormality of the retina associated with a hereditary process. "Retinal dystrophy panel genetic testing identified a heterozygous previously reported missense variant in IFT140, c.2611C > T, p.(Arg871Cys)." (PMID 36084042, 2023). "The deletion variant in IFT140 r.2765_2768 has previously been reported as a likely pathogenic variant in ClinVar (VCV000863072.3) in a patient with retinal dystrophy, as well as, a patient with MZSDS." (PMID 35873489, 2022). "The classical syndromic phenotype associated with variants in IFT140 includes skeletal abnormalities, renal disease, and retinal dystrophy." (PMID 30479745, 2018). "For example, it has been reported that mutations in IFT-A core components, specifically, IFT140, IFT144, and IFT-B peripheral component IFT17218,36,37, can cause both syndromic and nonsyndromic cases of retinal dystrophies." (PMID 28460050, 2017). "The V464L missense variant in human IFT140 (dbSNP: rs2034681207 and NP 055529.2) was submitted to ClinVar as a likely pathogenic for Retinal dystrophy, however, there is no functional evidence to support this claim." (PMID 37933433, 2023). "The presence of retinal dystrophy and chronic renal disease, the characteristic features of Mainzer–Saldino syndrome, reinforce monitoring of the other affected cases over time, as the IFT140 gene is reported to manifest both syndromic and non-syndromic phenotypes." (PMID 39766915, 2024).
Renal cyst (7 papers, 2018 to 2026). A fluid filled sac in the kidney. "There were no plausible second variants within IFT140 or other known cystic kidney genes in any of these individuals." (PMID 39190485, 2024).
Jeune syndrome (6 papers, 2013 to 2023). Jeune syndrome, also called asphyxiating thoracic dystrophy, is a short-rib dysplasia characterized by a narrow thorax, short limbs and radiological skeletal abnormalities including "trident" aspect of the acetabula and metaphyseal changes. "We support this with the identification of a recessively inherited IFT140 mutation in a patient with Jeune syndrome." (PMID 24009529, 2013). "IFT140 has recently been implicated in Mainzer-Saldino and Jeune syndromes and conditional deletion in mice causes a polycystic kidney phenotype." (PMID 24009529, 2013). "We also report the identification of a homozygous recessive mutation in IFT140 in a Jeune syndrome patient." (PMID 24009529, 2013). "We present the identification of a novel IFT140 mutation in a case of Jeune syndrome." (PMID 24009529, 2013). "The Jeune syndrome mice model established by IFT140 knockout showed dwarf phenotypes with decreased bone length, density, growth retardation, and disappearance of the growth plate." (PMID 36523493, 2022). "Mutations in the IFT140 gene are associated with isolated retinal dystrophy, Mainzer-Saldino (MSS) Syndrome, Jeune Syndrome (JATD) and Opitz trigonocephaly C syndrome (OTCS)." (PMID 32007091, 2020). "Based on the identification of an Ift140 mutation in this mouse model we also sequenced the human orthologue in a cohort of SRP and Jeune syndrome patients." (PMID 24009529, 2013). "The data presented here describes the first Ift140 mouse model of Jeune syndrome." (PMID 24009529, 2013). "IFT140 mutations (MIM 614620) are clinically associated with skeletal ciliopathies known as short rib thoracic dysplasia (SRTD) including Mainzer–Saldino syndrome (MIM 266920), asphyxiating thoracic dystrophy/Jeune syndrome (MIM 208500), and Sensenbrenner syndrome (MIM 614620)." (PMID 38079449, 2023). "Similarly, the IFT140 mutation described here in the patient with Jeune syndrome did not result in any obvious kidney dysfunction but this may be due to the early post-natal lethality of the condition in this case." (PMID 24009529, 2013).
retinitis pigmentosa (6 papers, 2021 to 2025). Retinitis pigmentosa (RP) is an inherited retinal dystrophy leading to progressive loss of the photoreceptors and retinal pigment epithelium and resulting in blindness usually after several decades. "CDHR1, TTLL5, PRPF6, and IFT140 have been reported to play roles in human disorders of cone-rod dystrophy and cone dystrophy or retinitis pigmentosa." (PMID 35456484, 2022).